CCL3 (C-C motif chemokine ligand 3)
Diseases named in the same sentence as CCL3 in open-access papers (continued):
Sharing a sentence is not in itself a finding about the gene and the disease.
tumor (continued). "IE1 tumors also had increased scores for chemotactic interactions, mainly mediated by CCL3, CCL4, CCL5, and CXCL9, suggesting a more dynamic immune environment with increased potential for recruitment of cells from outside the tumor." (PMID 36609566, 2023). "Cell–cell interaction analysis within tumor tissues also confirmed that TeMs participated actively in the recruitment of T cells through CXCL10/11–CXCR3, CCL3/4/5–CCR5 and CXCL12–CXCR4 signaling." (PMID 37488416, 2023). "For example, inflammatory SASP such as CCL3 and IL-6 remodels the TME by recruiting immunosuppressive cells, thus protecting tumor cells from immunosurveillance." (PMID 36675039, 2023). "Tumor tissue levels of CCL3 (MIP-1α) and IL-1β displayed significant positive correlation with the amount of HIF-1α in the tumor." (PMID 38273861, 2023). "Neutrophil cluster 6 also has high expression of Ccl2, Ccl3, Ccl4, Ccl5, and Cxcl2, which are inflammatory mediators involved in MDSC migration to and activation in the tumor microenvironment." (PMID 37483625, 2023). "N1 subtype secretes CCL3, CCL9, CXCL10, TNF-α, IL12, Cathepsin G, and neutrophil elastase (NE) to recruit, activate and induce proliferation of T-cells to implement anti-tumor influence and improve adaptive immune responses." (PMID 37376417, 2023). "As for chemokines, such as CCL2, CCL3 and CXCL1, their expressions in GISTs are relatively high and CCL2 induces the infiltration of macrophages into tumor tissues and promotes tumor growth." (PMID 37072770, 2023). "Tumor-localized IL9 also polarized TAMs toward M1 in vivo and made them release CCL3/4 and CXCL9/10 to recruit antitumor immune cells, including T and natural killer cells, into the tumor microenvironment." (PMID 36968220, 2023). "To explore the effect of the CCL3/VIRMA/SIRT1 pathway on the ICC malignant process, we constructed subcutaneous and orthotopic tumor models in nude mice." (PMID 36691046, 2023). "Low passage tumor alone secreted high concentrations of CCL2/MCP1, CXCL8/IL-8, CXCL1/GRO, IL-6, CXCL10/IP10, G-CSF, TGFβ1, MMP1, CCL3/MIPα, GM-CSF and EGF." (PMID 37063842, 2023). "In turn, the IL9-polarized macrophages secreted chemokines, including CCL3, CCL4, CXCL9, and CXCL10, to recruit antitumor T cells, NKs, DCs, and macrophages to infiltrate the tumor." (PMID 36968220, 2023). "According to recent data, tumor-infiltrating macrophages have been mostly described in those PitNETs with hypersecretion of CCL2, CCL3, CCL4, and IL-8." (PMID 37958702, 2023). "In the treated group, the LIVP-RFP cytokine analysis suggested elevation of CXCL10 in the tumor samples and IFN-α, IFN-γ, CCL2, CCL3, CXCL9, and CXCL10 in the sera samples." (PMID 37112810, 2023). "Our observations are consistent with previous observations highlighting the role of CCL3 and CCL4 chemokine systems in recruiting antitumor CD103+ DCs to the tumor, especially in the tumor models that respond poorly to CPIs." (PMID 36968220, 2023). "CCL2 and CCL3 influence monocyte recruitment and production of MMP9, thus promoting tumor invasion and metastasis." (PMID 37947617, 2023). "Macrophage 2 had enriched expression of many chemokines and ligands, including CCL4, CCL4L2, CCL3, and CCL3L1, which were involved in recruiting immune cells to promote tumor development." (PMID 36292645, 2022). "In vitro and in vivo data demonstrated that ATRi plus RT promoted the production of CCL3, CCL5, and CXCL10 in tumour cells." (PMID 35365161, 2022). "Higher percentages of ZsGreen+ cDCs were found in the lymph nodes of CCL3- and XCL1-overexpressing tumor models." (PMID 36654820, 2022). "Anti-tumor N1 TANs possess high levels of TNFα, CCL3, ICAM-1, and are also involved in the production of ROS which is cytotoxic to tumor cells." (PMID 36253762, 2022). "The results showed that knockout CCL3−/− mice and CCR5−/− wild-type C57BL/6 mice exhibited slower tumor proliferation, and the difference was statistically significant." (PMID 35935327, 2022).
tumor (continued). "They described that the recruitment of myeloid cells such as neutrophils, macrophages, and MDSCs to the tumor microenvironment by tumor cells promotes the secretion of active IL-1β and other proinflammatory mediators such as CCL2, CCL3, and Bv8." (PMID 35681719, 2022). "And IL-33 can stimulate the production of cytokines (IL-4, IL-6) and chemokines (CCL2, CCL3, CCL7, CXCL1), which are also involved in the construction of the tumor microenvironment." (PMID 36110250, 2022). "M-MDSCs are recruited to the TME primarily by tumor-derived CCL2 and CCL5, while PMN-MDSCs are recruited by CCL2 and CCL3." (PMID 35345849, 2022). "During hyperthermia, cells under heat stress enhance immune response by promoting the release of more exosomes rich in tumor antigens, chemokines (including CCL2, CCL3, CCL4, CCL5 and CCL20, etc.)and HSP to APC to identify and destroy tumor cells." (PMID 36032103, 2022). "A study using a kidney malignant tumor model found that knockout of the CCL3 and CCR5 genes in mice can reduce the incidence of tumor metastasis." (PMID 35935327, 2022). "CCL3/CCR1 is another pathway that is related to immune cells migration, inflammatory activation, immune responses, and tumor growth." (PMID 36499169, 2022). "CCL2, CCL3, CCL5, and CCL7 attract monocytes/macrophages to exert anti-infective, anti-tumor, and immunomodulatory effects at sites of inflammation." (PMID 36188003, 2022). "The B16F10 cells produced large amounts of CCL5/RANTES, whereas the ex vivo s.c. tumour also secreted CCL2/MCP-1 and, at much lower levels, CCL3/MIP-1α and CCL4/MIP-1β." (PMID 36241867, 2022). "The CD27-positive, CD38-positive, and PAX5-negative tumor-induced plasmablast-like-enriched B cell (TIPB) population regulates T cell-recruiting chemokines (CCL3, CCL4, and CCL5) and increases the number of tumor-infiltrating T cells." (PMID 36361781, 2022). "The role of the proinflammatory chemokines MIP1-α (CCL3), MIP1-β (CCL4), and MCP-1 (CCL2) in the tumor remains controversial." (PMID 35359980, 2022). "In both models, tumoral overexpression of CCL3, CCL19, CCL21, and XCL1 significantly repressed tumor growth, despite the differential overexpression levels in these cell lines." (PMID 36654820, 2022). "Tumor cells and MDSCs in the TME are able to secrete CCL3, CCL4, and CCL5, interacting with CCR5 on Tregs and attracting them into the TME." (PMID 35345849, 2022). "The role for CCR5 has been documented in T-cell recruitment to the tumor site, and local production of CCL5 or CCL3 induces selective recruitment of CD8 T cells and CTL-dependent tumor suppression in mouse models." (PMID 35530341, 2022). "In fact, the expression of key neutrophil-secreted chemokines, including CCL3, CCL4, CCL20, and CXCL12, was increased in the tumor supernatants of mice treated with 7HP349." (PMID 35552271, 2022). "In turn, neutrophils secrete numerous chemokines, such as CCL2 (MCP-1) and CCL3 (MIP-1), CCL19, and CCL20, to attract monocytes and dendritic cells into the tumor microenvironment." (PMID 36111233, 2022). "NK cells can directly kill tumor cells by cytotoxicity and can also exert immune functions indirectly by secretion of cytokines such as IFN-γ, TNF-α, CCL3, and CCL4." (PMID 35707003, 2022). "ATC-like tumor shows high levels of T cell infiltration, chemo-cytokines (CCL2, CCL3, CCL4, CCL5, CXCL9, and CXCL10), and immune checkpoints." (PMID 36293435, 2022). "Consistent with this, the expression of T cell chemokine genes such as CCL3, CCL4, CCL5, CXCL9, CXCL10 and CXCL1123 in MKN74 tumours tends to be higher than that in other tumours, especially after ERY974 administration." (PMID 36071036, 2022). "Overexpression of CCL3 in HCT116 cells accelerated tumor proliferation, and the difference in tumor diameter compared with the control group was statistically significant (P < 0.05)." (PMID 35935327, 2022).
tumor (continued). "In mouse CRC models, we demonstrated that all four chemokines, including CCL3, CCL19, CCL21, and XCL1, effectively inhibited tumor growth." (PMID 36654820, 2022). "Previous data indicate that CCL3/CCR1 signaling regulates tumor cell macrophage interactions that, once established, deliver a survival signal to the tumor cells through engagement of αV-integrin expressed on MAMs and VCAM1 on the tumor cell." (PMID 36077870, 2022). "There were also trends of increasing CCL3 and TNF-α expression in the tumor cells, indicating a slight pro-inflammatory effect in the solid tumors." (PMID 35513776, 2022). "In MM, it has been reported that both tumor cells and BM mesenchymal stromal cells produce chemokines such as CXCL12, CCL2, CCL3, and CCL14 that promote macrophage migration to the tumor niche and polarize macrophages towards an M2-like phenotype in vitro." (PMID 33435306, 2021). "Their interaction with the BMDMs and tumor cells in the collagen-I matrix increased production of GM-CSF, G-CSF, IL-6, CCL2, CCL3, CCL4 and CCL12, and reduced production of IFN-β1, LIF, VEGF, CCL17, CXCL5 and CX3CL1." (PMID 34572807, 2021). "In cancer, tumor cells and TAMs release the chemokines CXCL1/2/3/6/8 and CCL3/5, which induce neutrophils in peripheral blood to enter the TME and polarize into different TANs." (PMID 34925375, 2021). "CCL3 and CCL4 chemoattract the infiltration of neutrophils, macrophages, natural killer cells, and T cells to the tumor microenvironment." (PMID 36046113, 2021). "In the present study, inflammation-related chemokines including CCL3 and CCL4 were both increased in cSCC and AK, which helps recruit and CD4+, CD8+ T cell to kill tumor cells." (PMID 33664254, 2021). "TAMs are mainly recruited from the periphery by chemokines released from tumor tissues, including CCL2, CCL3, CCL4, CCL5 and CXCL12." (PMID 34925375, 2021). "Other chemokines known to regulate tumor development and progression include the CCR5 receptor ligands CCL3, CCL4, and CCL5." (PMID 33406733, 2021). "Neutrophils which exist in tumor microenvironment are capable of producing IL10 and CCL3 to promote tumor growth." (PMID 34123808, 2021). "A number of studies have shown differential expression of CCR5-related ligands (CCL3, CCL4, CCL5) in peripheral blood and tumor samples of CRC." (PMID 32902795, 2021). "In our in vivo model, however, properdin-deficient mice, when inoculated with logarithmically growing B16F10 cells, showed decreased levels in blood of the chemoattractants C5a and CCL2 and in tumour of the mediators CCL2, CCL3, IL-13, and TIMP-1." (PMID 33494138, 2021). "Neutrophils which exist in tumor microenvironment are capable of producing angiogenic chemokines and cytokines including CCL2,CCL3, CCL5, CCL10, IL4 and IL10 to promote tumor growth, invasion and angiogenesis." (PMID 34123808, 2021). "Our finding of higher concentrations of CCL3/MIP-1α, CCL4/MIP-1β and CXCL2/MIP-2 in old versus young stressed mice are consistent with greater tumor growth in old stressed mice and poorer prognosis." (PMID 34604038, 2021). "CCR5 binds many ligands which are overexpressed in the tumor microenvironment including CXCL13 (BCA-1), CCL3 (MIP1α), CCL3L1, CCL4 (MP-1β), CCL8 (MCP2), CCL11 (eotaxin), CCL13 (MCP-4), and CCL16 (HCC-4)." (PMID 33485378, 2021). "In contrast, CD8+ TILs showed elevated levels of inflammatory chemokine genes, CCL3 and CCL5, which are involved in the trafficking and recruitment of other immune cell populations to hinder tumor growth." (PMID 33916009, 2021). "CCL3 secretion by TAMs was found to be induced by CCL2/CCR2 and IL-33, with these TAMs reported to mediate metastatic spread in different tumor models." (PMID 34988021, 2021). "Its ligands CCL3, CCL4, and CCL5 are broadly expressed by a variety of normal cells and tumor cells, and frequently upregulated in tumor tissues of various types of cancer." (PMID 34885241, 2021).
tumor (continued). "While baseline IFNg is higher in the recurrent tumor, the level of TNFa, RANTES (CCL5), IP-10, IL-5, IL-10, MIP1a (CCL3), MIP1b (CCL4), and GM-CSF are all significantly lower in the recurrent tumor." (PMID 34221953, 2021). "CRISPR/Cas9-mediated editing of A2AR rendered CAR T cells resistant to NECA in terms of their capacity to secrete IFNγ, TNF, and MIP1α (CCL3) upon coculture with either OVCAR-3 cells or MCF7 cells, another Lewis Y+ tumor cell line." (PMID 34050151, 2021). "Tumor-conditioned monocyte shown an increased migration in response to CXCL5, CXCL12, CCL3, and CCL5." (PMID 34975843, 2021). "CCL3, CCL4, and CCL5 binding to the CCR5 receptor promote downstream signaling pathways that facilitate tumor cell proliferation, angiogenesis, metastasis, immune cell recruitment, and repolarization in gastrointestinal cancer." (PMID 33406733, 2021). "After a series of validation experiments for the concerned genes, it was found that IL6, GM‐CSF (CSF2), IL11, CCL3, S100A8 and S100A9 were significantly decreased in the gut tumours of ApcMin/+ TLR4−/− mice compared with ApcMin/+ WT mice." (PMID 31650683, 2020). "It has been shown that CX3CR1+ monocytes are recruited to the tumor cell aggregates in response to tumor-derived CX3CL1, where they can directly engage cancer cells or secrete CCL3, CCL4 and CCL5 to activate natural killer cells to kill CTCs." (PMID 33414786, 2020). "Specifically, first, tumor cells secrete a large number of chemokines to recruit macrophages into tumor tissues, such as CCL2, CCL3, CCL5, and so on." (PMID 33224886, 2020). "The mRNA expression of different pro-tumor factors such as interleukin-1β (IL-1β), CC-chemokine ligand-2-4 (CCL2, CCL3, CCL4), Interleukin-23 (IL-23) and inducible nitric oxide synthase (iNOS), was analyzed." (PMID 33049964, 2020). "Among the chemokine ligands tested, the CCR5 ligands CCL3 and CCL5 were remarkably upregulated in the tumour tissue compared to PTY cells or control skin." (PMID 32439888, 2020). "In multiplex antibody arrays assays the majority of cytokines in tumor tissue and mouse plasma were alike, with the exception of IL-16, CCL12 and CCL3 whose expression was increased in tumor tissues." (PMID 31885880, 2020). "In tumor-infiltrate Tregs, we found that IFIT2, CCL3, RBPJ, etc. were upregulated in GC tissues compared to adjacent normal tissues while IGJ, XCL1, XCL2, etc. were downregulated." (PMID 32039830, 2020). "Tumor-infiltrating NK cells differentiate into two main populations with distinct profiles of chemokine gene expression: XCL1+XCL2+ NK cells and CCL3+CCL4+CCL4L2+CCL5+ NK cells." (PMID 33424862, 2020). "Elevated levels of IL-6, IL-12, CCL2, CCL3, CCL5, CXCL9 would a priori predict for a greater infiltration of the tumor by M1 type macrophages, which independently confirms our prior IHC staining findings." (PMID 31885880, 2020). "Circulating monocytes are recruited by several tumor-derived chemo-attractants as CCL2 (MCP-1), CCL3 (MIP-1), CXCL12 (SDF-1), and CSF-1 at tumor sites where they differentiate into TAMs and facilitate tumor progression." (PMID 33374253, 2020). "The effect of chronic hypoxia on CCL3/MIP-1α and CCL4/MIP-1β expression in a tumor cell depends on the type of tumor." (PMID 32781743, 2020). "At the gene level, most tumor-infiltrating MAIT cells expressed CCL4, CCL3, and RGS1, indicating a high response to inflammation." (PMID 33205061, 2020). "CCL3/MIP-1α and CCL4/MIP-1β are highly produced in the culture supernatant and cytoplasmic fractions of tumor-infiltrating lymphocytes." (PMID 32231656, 2020). "Together, these results indicate that sustained release of CCL3 and CCL4 is sufficient to promote CCR5-dependent homing into tumours in vivo, and that the presence of tumour-reactive CTLs in a tumour promotes the recruitment of distant CCR5+ CTLs." (PMID 33046212, 2020). "The chemokines CCL3 and CXCL12 represent contrasting examples of induced and constitutive production by tumor and bystander cells." (PMID 32899476, 2020).
tumor (continued). "The CCL3 and CCR5 expression levels in the tumor nests were assessed and divided into low and high groups based on the staining intensity." (PMID 32457351, 2020). "The interaction of tumor-antigen presenting dendritic cells and CD4+ T helper cells releases chemokine CCL3 and CCL4 that in turn attract CCR5+ cytotoxic CD8+ T cells." (PMID 33414786, 2020). "Herein, we detected immunoreactivities for both CCL3 and CCR5 in the tumor nests of human ESCC tissues." (PMID 32457351, 2020). "Mature DCs can also secrete cytokines to foster T cell response and release chemokines such as CXCL9, CXCL10, CCL3, CCL4, and CCL17 to recruit T cells into the tumor bed." (PMID 33505304, 2020). "We demonstrated that human MSCs secreted high levels of CCR5 ligands (i.e., CCL3, CCL4, and CCL5), and that MSCs promoted CRC tumor growth in vivo via CCR5 signaling." (PMID 30890699, 2019). "Among the others, CCL2, CCL3, and CCL5 contribute to tumor vascularization and metastasis and also stimulate MMP9 secretion by monocytes, which strongly favors tumor cell extravasation." (PMID 31484464, 2019). "Tumor-associated CD8+ T cells expressing exhaustion markers across all four tumor types project onto activated CD8+ T cells in our map, and express genes within the Cytokine module (CCL3, CCL4, XCL1, XCL2, and IFNG), and to a lesser extent Cytotoxic module." (PMID 31624246, 2019). "Further, MDSCs have been reported to produce CCL3, CCL4, and CCL5 chemokines favoring tumor recruitment of Treg cells." (PMID 31484464, 2019). "Ninety percent of PitNETs secreted IL-8, CCL2 and CCL3, while CXCL1 was secreted by 50% of the tumours." (PMID 31703742, 2019). "In particular, the chemokines CCL2, CCL3, IL-8/CXCL8, and CXCL12 are consistently involved in promoting osteoclastogenesis and tumor growth." (PMID 29930538, 2018). "Still, even small wounds to the tumor created by needle biopsy can rapidly promote pro-inflammatory factors such as S100A8, CXCL2, CCL3, and COX2 followed by a significant increase in the number of myeloid derived suppressor cells in the tumor." (PMID 29728948, 2018). "Neutrophils are recruited at the tumor sites by several chemokine signals, such as CXCL12, CXCL8, CCL3 (MIP-1α), and CXCL6 (huGCP-2), or murine chemokines CXCL1, CXCL2, and CXCL5." (PMID 30591657, 2018). "The increase in IL-6, IL-12, CCL2, CCL3, CCL5, CXCL9 levels would a priori predict for elevated levels of M1 type macrophages in the tumor, which independently validates our prior IHC staining findings." (PMID 29137331, 2017). "In the context of OSCC, one study previously showed the expression of CCL3 and CCR1 in tumour samples and metastatic lymph nodes and correlated it with poor cumulative survival." (PMID 28881626, 2017). "Herein, the increase of Ccl3, Ccr1 and Ccr5 in SCC mouse tumours is indicative of contribution of these molecules to oral carcinogenesis." (PMID 28881626, 2017). "In aggressive malignancies, metastatic MAMs arrive at secondary sites and in turn recruit inflammatory CCR2 bearing monocytes by CCL2, which in themselves release CCL3 and express CCR1, amplifying tumor potential." (PMID 28441391, 2017). "CDDO-Me also inhibited expression of chemokines that mediate selective recruitment of TAMs and M2 macrophages, (CCL3, CCL4, and eotaxin) and monocytic infiltration of tumor sites (CCL2 and CCL5)." (PMID 26918785, 2016). "Serum levels of CCL3 were positively related to the tumor size, while the CCL2/CCL3 ratio in OSCC patients was correlated to TNM (tumor, node, metastasis)." (PMID 27044404, 2016). "Next, we intravenously inoculated 5TGM1 cells into the mice and treated them with either control IgG or neutralizing antibodies against CCL3 or CCL2 (100 μg per mouse each time, intraperitoneally injected 1 day before and 7 days after tumor cell inoculation)." (PMID 26155942, 2015).